IL2RA (interleukin 2 receptor subunit alpha)
Diseases named in the same sentence as IL2RA in open-access papers (continued):
Sharing a sentence is not in itself a finding about the gene and the disease.
autoimmune disease (continued). "Several of these genes such as IL2RA and PFKFB3 have previously been implicated in the development of autoimmune diseases or play a role in critical T cell pathways, suggesting these genes are likely targets that explain the molecular function of the risk variants." (PMID 35773720, 2022). "Notably, many of the IL2RA SNPs related to autoimmune diseases fall into this region and affect transcription factor binding and enhancer activity." (PMID 33193091, 2020). "Outside the HLA region the IL2RA polymorphism rs706778 is associated with increased risk of type 1 diabetes, autoimmune thyroid disease (AITD) and coeliac disease, as well as other paediatric-onset autoimmune disorders." (PMID 29417186, 2018). "Furthermore, three loci which previously have been implicated in JIA and several other autoimmune diseases – the PTPN22 locus on 1p13, the IL2RA locus on 10p15, and the ANTXR2 locus on 4q21.21 – were nominally associated with JIA." (PMID 27005825, 2016). "The genetic heterogeneity found at the IL2RA locus could help explain patterns of concomitance with other autoimmune diseases." (PMID 26133380, 2015). "Furthermore, we wanted to highlight allelic heterogeneity at the IL2RA locus between various autoimmune diseases." (PMID 26133380, 2015). "One human patient, homozygous for a 4 base pair exonic deletion in IL2RA, lacking a functional IL-2RA demonstrated increased susceptibility to viral, bacterial and fungal infections, but unlike Il2ra-deficient mice did not develop overt autoimmune disease." (PMID 19265545, 2009). "Our findings demonstrate that the association between IL2RA and autoimmune disease is not a simple one." (PMID 19265545, 2009). "Additionally, key genes such as IL2RA and CD247, linked with risk genes PTPN22, PTPN2, and RUNX1, are consistently implicated across multiple conditions, including RA, lupus erythematosus, B-cell lymphomas, and autoimmune diseases." (PMID 40839671, 2025). "Furthermore, it can be postulated that different SNPs in TYK2 and IL2RA may play different roles in various types of autoimmune diseases." (PMID 38332917, 2023). "Several genes within the IL-2/IL-2R pathway (e.g., IL2, IL2RA, IL2RB, and PTPN2) may influence an individual’s susceptibility to human autoimmune diseases, with evidence to suggest that these genes exert their effects by altering Treg cell frequency or function." (PMID 33916798, 2021). "According to the literature genes encoding IL2RA (alpha subunit of Interleukin 2 receptor), IFIH1 (Interferon induced with helicase C domain 1) and CTLA-4 (cytotoxic T cell antigen 4) might be associated with autoimmune diseases pathogenesis." (PMID 32974248, 2020). "Furthermore, there is precedent for this because the PTPN22 gene has been associated with a variety of autoimmune diseases, although, interestingly and unlike the IL2RA/CD25 gene, not with MS." (PMID 19116909, 2009). "CD25 (also named as interleukin-2 α-chain receptor (IL-2RA)) is highly expressed in CD4 Tregs, which is vital for Treg function and the pathogenesis of many autoimmune diseases." (PMID 35083339, 2022). "Irrespective of this, two candidate causal SNPs and genes including rs3087243 (RAPH1) and rs61839660 (IL2RA, RBM17, PFKFB3, LINC02649) were found to be common between T1D and other autoimmune diseases." (PMID 35773720, 2022). "Candidate gene mapping involving variant annotation, finemapping, and colocalisation analyses, and data from mouse models highlights the involvement of genes with a known role in autoimmune disease (PTPN22, HLA, IL2RA, and AIRE)." (PMID 34145262, 2021). "Top SNPs shared between RA and CD, as well as RA and UC or UC and CD, lie in regions well-known to be shared across multiple autoimmune diseases, such as the HLA, IL23R, TNFAIP3, and IL2RA." (PMID 29309429, 2018).
autoimmune disease (continued). "Thus, we hypothesized that decreased response to IL-2 may be a common phenotype of subjects who have autoimmune diseases associated with variants in the IL2RA locus, including T1D and MS, particularly in cells expressing the high affinity IL-2R alpha chain (IL-2RA or CD25)." (PMID 24376757, 2013). "Genome-wide association studies (GWASs) have also identified several non-HLA genetic variants linked to MS, including those in the interleukin-7 receptor (IL7RA), interleukin-2 receptor (IL2RA), CD58, and CLEC16A genes, indicating a shared genetic foundation with other autoimmune diseases." (PMID 40724862, 2025). "In addition, a series of studies have demonstrated that IL2RA and IL2RB participate in inflammatory processes in various human autoimmune diseases such as type I diabetes, rheumatoid arthritis (RA), and multiple sclerosis (MS)." (PMID 34485395, 2021). "Thus, other factors in addition to IL2RA and PTPN2 genotype likely contribute to reduced response to IL-2 in these two autoimmune diseases." (PMID 24376757, 2013). "Additionally, genetic associations between different polymorphisms located within the IL2/IL21 region as well as within both IL2RA and IL2RB loci and several autoimmune diseases have also been reported." (PMID 23676143, 2013). "In addition to the HLA and CTLA4 gene loci, there are confirmed associations (2 or more reports) for a number of genes also common to many autoimmune diseases: PTPN22, CD40, IL2RA (CD25), and FCRL3." (PMID 22530160, 2012). "Our results indicate that the analyzed IL2RA and IL2RB polymorphisms do not seem to play a significant role on the non-anterior uveitis genetic predisposition, similar to what has been reported in other autoimmune diseases such as inflammatory bowel disease and celiac disease." (PMID 23676143, 2013).
Autoimmunity (55 papers, 2004 to 2026). The occurrence of an immune reaction against the organism's own cells or tissues. "Loss-of-function variants in IL2RA cause a very rare autosomal recessive disorder marked by early-onset autoimmunity and recurrent infections with an IPEX-like presentation." (PMID 41694357, 2026). "Suspicion of IL2RA deficiency arises in patients with recurrent infections including viral infections, autoimmunity, and lymphoproliferation." (PMID 39859044, 2025). "Complete IL2RA deficiency can lead to severe autoimmunity with IPEX like symptoms, and IL2RA variants have been associated with reduced Treg numbers, suboptimal Treg function, and an increased risk for development of T1D." (PMID 36032083, 2022). "Patients with mutations in IL2RA can have severe enteritis, viral infection susceptibility, pronounced lymphoproliferation, autoimmunity, and an IPEX-like syndrome." (PMID 35493508, 2022). "We recently identified a conserved autoimmunity-associated IL2RA intronic enhancer that controls the timing of gene expression in response to T-cell stimulation." (PMID 30793048, 2019). "As a case study, we considered IL2RA locus, which was one of the first to emerge from early GWAS as an autoimmunity risk factor." (PMID 28234966, 2017). "In humans, the presence of an autoimmunity-associated IL2RA haplotype correlates with reduced interleukin-2 responsiveness in stimulated CD4+ T cells and decreased ability of Tregs to suppress the proliferation of autologous effector T cells." (PMID 24154763, 2013). "This is demonstrated most dramatically in knock-out mice in which a deficiency of Il2, Il2ra, or Il2rb leads to early death due to severe autoimmunity." (PMID 24376757, 2013). "Genetic evidence linking the IL-2/IL-2RA pathway to the predisposition of human autoimmunity, and in particular T1 D, has also emerged in recent years." (PMID 21059266, 2010). "We used this approach to annotate autoimmunity-associated SNPs of IL2RA locus." (PMID 28234966, 2017). "Genetic association of the IL2RA locus with autoimmunity is complex." (PMID 24376757, 2013). "In order to investigate whether autoimmunity risk at IL2RA was due to distinct or shared alleles, we performed a genetic association study of three IL2RA variants in a DNA collection of up to 9,407 healthy controls, 2,420 MS, and 6,425 T1D subjects as well as 1,303 MS parent/child trios." (PMID 19119414, 2009). "Biallelic loss-of-function (LOF) variants in the alpha subunit of IL2RA (CD25), which forms a high-affinity IL-2 receptor with IL2RB and CD132, lead to an autosomal recessive immunodeficiency characterized by autoimmunity and eczema." (PMID 39859044, 2025). "In fact, many MS risk genes are involved in autoimmunity, such as the human leukocyte antigen class II allele HLA-DBR1*15:01 and the interleukin 2 receptor subunit alpha (IL2RA)." (PMID 38845026, 2024). "Although coding mutations that ablate IL2RA expression result in severe immunodeficiency and autoimmunity, the functional consequences of non-coding variation at the IL2RA locus have proven more difficult to characterise." (PMID 36897113, 2023). "We screened all participants for the seven genes known to cause monogenic autoimmunity that can include diabetes (AIRE, IL2RA, FOXP3, LRBA, STAT1, STAT3, STAT5B)." (PMID 29417186, 2018). "A reasonable hypothesis is that the genetic risk for autoimmunity is greater in individuals and families with multiple diagnoses of AIDs, and that for example the SNPs strongly associated with multiple AIDs (such as IL2RA or PTPN22) would be associated with clustering of these diseases." (PMID 29182645, 2017). "Its polymorphic variants are strongly associated with T1D and affect the soluble receptor levels, although discrepancies in the effect of the IL2RA genotype on serum measurements were detected in different autoimmune conditions." (PMID 24154763, 2013).
Autoimmunity (continued). "The loci that were associated with the largest number of ADs include IL23R, TNFAIP3, and IL2RA, supporting an important role for T cell and innate immune response pathways in autoimmunity." (PMID 22174698, 2011). "In the IL-2RA gene region, a GWA study for MS risk alleles and a large-scale fine-mapping study in T1D provided compelling evidence for a shared autoimmunity locus." (PMID 19119414, 2009). "Loss-of-function mutations in IL2RA cause the autosomal recessive IEI CD25 deficiency, a disease of immune dysregulation featuring T regulatory cell defects, recurrent infection, lymphoproliferation, atopy, and autoimmunity." (PMID 39241920, 2024). "The activation of effector T cells as the main function of IL-2 was contested when ablation of Il2, Il2ra and Il2rb expression in mice caused lethal lymphoproliferation and autoimmunity, rather than immunodeficiency." (PMID 37741949, 2023). "Interestingly, enhancer disruption of IL2RA delayed its expression, which was eventually recovered three days after T cell stimulation, implying that the induction of autoimmunity could happen in a transient and tissue specific manner." (PMID 30060490, 2018). "IL2RA is targeted by several known drugs (e.g., HuMax-TAC), with indications on autoimmune diabetes, and has known roles in the pathogenesis of autoimmunity." (PMID 32879140, 2020). "We aimed to investigate for the first time the potential influence of the IL2/IL21, IL2RA and IL2RB most associated polymorphisms with autoimmunity on the endogenous non-anterior uveitis genetic predisposition." (PMID 23676143, 2013). "IL2RA/CD25–knockout mice develop severe systemic autoimmune disease, a paradoxical finding suggesting that the gene is needed for down-regulation of immune responses in order to prevent autoimmunity." (PMID 19116909, 2009).
type 1 diabetes (49 papers, 2004 to 2025). "Gene–gene interactions were noted between GIMAP4 and IL2RA, a known human type 1 diabetes risk gene, as well as between GIMAP5 and INS, a major type 1 diabetes risk gene strongly associated with insulin autoantibodies as the first appearing islet autoantibody." (PMID 41042382, 2025). "The co-localisation of IL2RA expression in CD8+ effector memory T cells with type 1 diabetes risk is further supported by the previous reports of IL-2 impairment leading to CD8+ T cell exhaustion, potentially driven by both acute and chronic viral infections." (PMID 39271518, 2024). "A previous small study showed that rs12722495, which is in strong LD (r2=0.89) with our lead IL2RA eQTL and type 1 diabetes risk locus rs61839660 near IL2RA, decreased IL2RA expression in Tregs as well as their sensitivity to IL-2." (PMID 39271518, 2024). "We found evidence for a shared causal variant between the risk of type 1 diabetes and whole-blood IL2RA (rs61839660, posterior probability 100%), IL6R (rs10908839, posterior probability 96.5%) and IL6ST gene expression (rs7731626, posterior probability 97.0%)." (PMID 39271518, 2024). "The SNP rs61839660 is located in intron 7 of IL2RA and is known for associations with multiple autoimmune and atopic diseases including Crohn's disease, type 1 diabetes, asthma and allergic disease, and eczema." (PMID 39241920, 2024). "For example, enrichment of AP4 is detected at the interleukin 2 receptor alpha (IL2RA) SNP rs12722522*C, which is associated with type 1 diabetes." (PMID 33567514, 2021). "In 2013, measuring CD25 in T cells only and using about 8.2 million variants, an overlapping association between CD25hi effector T cells and type 1 diabetes was found in the IL2RA region." (PMID 34531863, 2021). "The IL2RA region was initially found to be associated with type 1 diabetes using a multi-locus genetic association test in 2005." (PMID 30060490, 2018). "Genomic region covering IL2RA is known to harbor the susceptibility loci for multiple sclerosis and type 1 diabetes." (PMID 29179475, 2017). "Multiple independent association signals within the IL2RA region confer risk to type 1 diabetes and are associated with sCD25 concentrations." (PMID 24264051, 2014). "We know that genetic variation in the IL2RA region is associated with susceptibility to type 1 diabetes, multiple sclerosis, Graves’ disease, rheumatoid arthritis, Crohn’s disease, systemic lupus erythematosus and juvenile idiopathic arthritis." (PMID 24264051, 2014). "To demonstrate PWAS in a disease relevant context, we also report differential transcription factor binding to type 1 diabetes- (T1D-) associated SNPs at the IL2RA or CD25 locus." (PMID 23028375, 2012). "For the IL2RA we have analyzed a wide region of the locus including the variants that have been associated to the MS and type 1 Diabetes (T1D)." (PMID 22363405, 2012). "To cover the much larger IL2RA locus, we typed 25 SNPs, including some for which significant association with type-1 diabetes has been reported." (PMID 22479496, 2012). "With the motivation of understanding the molecular effects of type 1 diabetes (T1D) risk variants located in the IL2 receptor α-chain (IL-2RA/CD25) gene region, we quantified cell surface expression of CD25 on CD4+ T cells using flow cytometry." (PMID 20049162, 2009). "Interestingly, our lead rs61839660 near IL2RA, which was associated with increased IL2RA expression and decreased risk of type 1 diabetes, was previously shown to be associated with higher risk of Crohn’s disease and lower risk of type 1 diabetes." (PMID 39271518, 2024). "Reduced expression of IL2RA on the surface of immune cells has been known to cause chronic immune suppression and may be linked to type 1 diabetes mellitus." (PMID 27887572, 2016).
type 1 diabetes (continued). "Previously, we showed that variants in IL2RA that predispose to type 1 diabetes reduce the level of IL-2RA/CD25 on Tregs and memory Teff cells, thereby potentially increasing the amount of homeostatic IL-2 production required for Treg survival and function, and limiting Tfh differentiation." (PMID 25652388, 2015). "Also genetic variation in the IL2RA locus has an evident functional relevance, clearly demonstrated by its association with rheumatoid arthritis, type-1 diabetes and multiple sclerosis." (PMID 22479496, 2012). "The IL2RA gene has also been associated with type 1 diabetes (T1D) and localized the association region in two independent groups of SNPs, spanning overlapping regions of 14 and 40 Kb encompassing IL2RA intron 1 and the 5′ regions of IL2RA and the RNA binding motif protein 17 (RBM17) genes." (PMID 19125193, 2009). "Here we perform a replication and fine mapping of the IL2RA gene region analyzing 3 SNPs previously associated with multiple sclerosis (MS) and 5 SNPs associated with type 1 diabetes (T1D) in a collection of 798 MS patients and 927 matched Caucasian controls from the south of Spain." (PMID 19125193, 2009). "Statistical fine-mapping indicates that the human IL2RA locus contains multiple independent signals, including one association refined to a single putative causal variant (rs61839660 C>T) that paradoxically confers risk for Crohn's disease but protection against type 1 diabetes mellitus." (PMID 36897113, 2023). "Single nucleotide polymorphisms (SNPs) in the interleukin 2 receptor alpha (IL2RA) gene have been suggested to be associated with type 1 diabetes (T1D) susceptibility." (PMID 26249556, 2015). "We did not observe such robust evidence for co-localisation between IL2RA, IL6R, IL6ST or TYK2 eQTL and the risk of type 1 diabetes in other cell types or in spleen or pancreas." (PMID 39271518, 2024). "The OR (95% CI) of type 1 diabetes per 1-SD increase in the genetically proxied gene expression of IL2RA, IL6R and IL6ST were 0.22 (0.17, 0.27), 1.98 (1.48, 2.65) and 1.90 (1.45, 2.48), respectively." (PMID 39271518, 2024). "IL2RA expression in CD8+ effector memory T cells co-localised (posterior probability 99.4%) with type 1 diabetes risk, with the lead causal variant rs61839660 being the same as for whole-blood IL2RA mRNA expression." (PMID 39271518, 2024). "Thus, higher blood IL2RA expression could be a sign of increased quantity and function of Tregs, which maintain a level of tolerance towards self-peptides and decrease the risk of type 1 diabetes." (PMID 39271518, 2024). "Genome-based approaches for identifying genetic polymorphisms associated with Type 1 diabetes (such as IL-2RA and CUX2) have revealed specific SNPs (such as PTPN22, IL-10, IL-27, and IL18RAP) with contrasting effects on the development of Type 1 diabetes." (PMID 38474087, 2024). "Apart from the HLA complex, which remains by far the strongest predictor of type 1 diabetes mellitus, the most important loci conferring susceptibility are located in the INS, PTPN22, IL2RA, SH2B3 genes." (PMID 34556755, 2021). "To provide insight into how the pipeline performed at another well studied locus in the context of Type 1 Diabetes, we focused on the IL2RA locus." (PMID 34543288, 2021). "To study which specific blood immune cells or tissues mediate the association between IL2RA, IL6R, IL6ST and TYK2 expression and type 1 diabetes risk, we analysed their pairwise co-localisation with type 1 diabetes risk in spleen, pancreas and subsets of blood immune cells." (PMID 39271518, 2024). "By tiling a 178-kilobase region around IL2RA in Jurkat-dCas9-VP64 cells, the screen uncovered six putative enhancers, including an intronic region containing rs61839660 – the SNP associated with Crohn's disease and type 1 diabetes mellitus." (PMID 36897113, 2023).